SGK1 (serum/glucocorticoid regulated kinase 1)
Description:
Serine/threonine-protein kinase which is involved in the regulation of a wide variety of ion channels, membrane transporters, cellular enzymes, transcription factors, neuronal excitability, cell growth, proliferation, survival, migration and apoptosis. Plays an important role in cellular stress response. Contributes to regulation of renal Na(+) retention, renal K(+) elimination, salt appetite, gastric acid secretion, intestinal Na(+)/H(+) exchange and nutrient transport, insulin-dependent salt sensitivity of blood pressure, salt sensitivity of peripheral glucose uptake, cardiac repolarization and memory consolidation. Up-regulates Na(+) channels: SCNN1A/ENAC, SCN5A and ASIC1/ACCN2, K(+) channels: KCNJ1/ROMK1, KCNA1-5, KCNQ1-5 and KCNE1, epithelial Ca(2+) channels: TRPV5 and TRPV6, chloride channels: BSND, CLCN2 and CFTR, glutamate transporters: SLC1A3/EAAT1, SLC1A2 /EAAT2, SLC1A1/EAAT3, SLC1A6/EAAT4 and SLC1A7/EAAT5, amino acid transporters: SLC1A5/ASCT2, SLC38A1/SN1 and SLC6A19, creatine transporter: SLC6A8, Na(+)/dicarboxylate cotransporter: SLC13A2/NADC1, Na(+)-dependent phosphate cotransporter: SLC34A2/NAPI-2B, glutamate receptor: GRIK2/GLUR6. Up-regulates carriers: SLC9A3/NHE3, SLC12A1/NKCC2, SLC12A3/NCC, SLC5A3/SMIT, SLC2A1/GLUT1, SLC5A1/SGLT1 and SLC15A2/PEPT2. Regulates enzymes: GSK3A/B, PMM2 and Na(+)/K(+) ATPase, and transcription factors: CTNNB1 and nuclear factor NF-kappa-B. Stimulates sodium transport into epithelial cells by enhancing the stability and expression of SCNN1A/ENAC. This is achieved by phosphorylating the NEDD4L ubiquitin E3 ligase, promoting its interaction with 14-3-3 proteins, thereby preventing it from binding to SCNN1A/ENAC and targeting it for degradation. Regulates store-operated Ca(+2) entry (SOCE) by stimulating ORAI1 and STIM1. Regulates KCNJ1/ROMK1 directly via its phosphorylation or indirectly via increased interaction with SLC9A3R2/NHERF2. Phosphorylates MAPT/TAU and mediates microtubule depolymerization and neurite formation in hippocampal neurons. Phosphorylates SLC2A4/GLUT4 and up-regulates its activity. Phosphorylates APBB1/FE65 and promotes its localization to the nucleus. Phosphorylates MAPK1/ERK2 and activates it by enhancing its interaction with MAP2K1/MEK1 and MAP2K2/MEK2. Phosphorylates FBXW7 and plays an inhibitory role in the NOTCH1 signaling. Phosphorylates FOXO1 resulting in its relocalization from the nucleus to the cytoplasm. Phosphorylates FOXO3, promoting its exit from the nucleus and interference with FOXO3-dependent transcription. Phosphorylates BRAF and MAP3K3/MEKK3 and inhibits their activity. Phosphorylates SLC9A3/NHE3 in response to dexamethasone, resulting in its activation and increased localization at the cell membrane. Phosphorylates CREB1. Necessary for vascular remodeling during angiogenesis. Sustained high levels and activity may contribute to conditions such as hypertension and diabetic nephropathy. Isoform 2 exhibited a greater effect on cell plasma membrane expression of SCNN1A/ENAC and Na(+) transport than isoform 1.
Synonyms: SGK
Tractability: Small molecule: a structure with a bound ligand is known; a high-quality ligand is known; it has a high-quality binding pocket; it belongs to a druggable protein family. Antibody: UniProt places it where antibodies can reach, with medium confidence; its Gene Ontology location is reachable by antibodies, with medium confidence. PROTAC: UniProt records ubiquitination sites on it; ubiquitination databases record sites on it; a small molecule that binds it is known.
Target class: AGC protein kinase group; AGC protein kinase SGK family; Enzyme; Kinase; Protein Kinase
Chemical probes: SGK1-IN-1 (high quality)
Gene: Protein-coding gene on chromosome 6 (134,169,248 to 134,318,112, reverse strand). Ensembl gene ENSG00000118515.
Subcellular location: Cytoplasm; Nucleus; Endoplasmic reticulum membrane; Cell membrane; Mitochondrion; Cell membrane (Isoform 2)
Subcellular location (Human Protein Atlas): Nuclear speckles
Pathways (Reactome):
Signal Transduction: NGF-stimulated transcription; PIP3 activates AKT signaling
Transport of small molecules: Stimuli-sensing channels
Gene Ontology:
Molecular function: protein binding; protein serine/threonine/tyrosine kinase activity; calcium channel regulator activity; chloride channel regulator activity; potassium channel regulator activity; protein serine/threonine kinase activity; sodium channel regulator activity; ATP binding; protein kinase activity; protein serine kinase activity
Biological process: intracellular signal transduction; neuron projection morphogenesis; regulation of blood pressure; renal sodium ion absorption
Cellular component: nuclear speck; cytoplasm; cytosol; nucleoplasm; nucleus; endoplasmic reticulum membrane; mitochondrion; plasma membrane
Genetic constraint (gnomAD): Loss-of-function variants: 23 observed, 45.54 expected, observed/expected ratio (o/e) 0.51, 90% interval 0.36 to 0.72. The upper end of that interval is the gene's LOEUF score, 0.72, which puts it in group 2 of 6, group 1 being the genes least tolerant of losing a copy. Missense variants: 411 observed, 547.24 expected, observed/expected ratio (o/e) 0.75, 90% interval 0.69 to 0.81. Synonymous variants: 221 observed, 211.03 expected, observed/expected ratio (o/e) 1.05, 90% interval 0.94 to 1.17.
Homologues: Orthologues: chimpanzee SGK1 (99% identical), macaque SGK1 (98% identical), dog SGK1 (96% identical), guinea pig SGK1 (96% identical), rabbit SGK1 (95% identical), mouse Sgk1 (94% identical), tropical clawed frog sgk1 (81% identical), rat Sgk1 (80% identical), pig SGK1 (77% identical), Drosophila melanogaster dop (29% identical), Caenorhabditis elegans kin-4 (27% identical), Caenorhabditis elegans wts-1 (22% identical), and 3 more. Paralogues in human: SGK3 (56% identical), SGK2 (49% identical), MAST4 (33% identical), MAST2 (32% identical), MAST1 (32% identical), MAST3 (31% identical), LATS2 (27% identical), LATS1 (26% identical), DMPK (23% identical), STK32C (22% identical), MASTL (22% identical), STK32B (20% identical), and 1 more.
Diseases named in the same sentence as SGK1 in open-access papers:
SGK1 is named in the same sentence as 241 diseases in open-access papers, as found by Europe PMC text mining. Sharing a sentence is not in itself a finding about the gene and the disease. The quoted sentences say what the papers report.
breast cancer (61 papers, 2006 to 2025). A primary or metastatic malignant neoplasm involving the breast. "Since then, several lines of evidence proved the role of SGK1 in breast cancer, as SGK-1 overexpression was frequently detected, and activation or upregulation of SGK1 was implicated in proliferation and metastatic ability of breast cancer." (PMID 35761157, 2022). "Specific examples of ESR1 fusion–induced genes in the MOTERA signature that are related to metastasis include SGK1, which encodes serum- and glucocorticoid-inducible kinase 1 and promotes breast cancer bone metastasis." (PMID 34711608, 2021). "In breast cancer cell lines, dexamethasone (a glucocorticoid) at 1000 nM inhibited chemotherapy-induced apoptosis and promoted the gene expression of SGK1 and MKP1, whose proteins are associated to cell survival." (PMID 34611221, 2021). "In breast cancer, ERα expression was associated with mTORC1-mediated phosphorylation of SGK1-Ser422." (PMID 32280568, 2020). "Breast cancer cell lines carrying mutations in PTEN or PI3K that also express high levels of SGK1 display inherent resistance to PI3K or Akt inhibitors." (PMID 31665227, 2019). "The sensitivity of a group of breast cancer cell lines possessing mutations that activate the PI3K pathway to Akt inhibitors has been correlated with the expression of SGK1 in cell lines including ZR‐75‐1, CAMA‐1 and T47D (utilised in this study)." (PMID 27481935, 2016). "The serine/threonine kinase SGK1 was initially identified in mammary tumor cells and is a critical element of oncogenic signaling pathways associated with tumor proliferation, cellular transformation, and resistance to radiation and chemotherapy." (PMID 41326907, 2025). "SGK1 has been identified as a response gene induced by serum and glucocorticoids in rat mammary tumor cells and is a typical GR response gene." (PMID 39246627, 2024). "1. siNDRG1 promoted migration/invasion of MDA-231 breast cancer cells, an effect that was inhibited by treatment with an SGK1 inhibitor." (PMID 38611020, 2024). "GCR and its downstream targets, SGK1 and Bcl-2, are critical for several biological processes influencing breast cancer growth and progression." (PMID 37370761, 2023). "Our group has previously identified progesterone-responsive microRNAs that regulate expression of PR and SGK1 in breast cancer." (PMID 37395734, 2023). "We measured the expression of SGK1 and Bcl-2, in respective breast cancer tissue arrays, from a multiracial cohort of breast cancer patients." (PMID 37370761, 2023). "The main objective of this study is to evaluate the expression of SGK1 and Bcl-2 in breast cancer tissue." (PMID 37370761, 2023). "SGK1 expression is upregulated in some tumors, such as breast cancer, multiple myelomas, and lung cancer, and it is downregulated in others, such as prostate cancer." (PMID 37370761, 2023). "Apoptosis is an important mechanism in the pathogenesis of breast cancer, and SGK1 was shown to regulate several biological processes in the cell, including apoptosis." (PMID 37370761, 2023). "As expected, GCR expression was positively correlated with SGK1 expression in breast cancer tissue, as glucocorticoids induce the SGK1 protein expression." (PMID 37370761, 2023). "We observed the same upregulation of cytoplasmic SGK1 in fibroadenoma and all subtypes of breast cancer tissue, compared to normal tissue, when SGK1 was categorized according to the median H score (low < 30 and high 30)." (PMID 37370761, 2023). "Our results showed an increase in the expression of SGK1 in breast cancer tissue compared to benign tissue." (PMID 37370761, 2023). "We also evaluated the correlation of GCR, SGK1, and Bcl-2 with overall survival and breast cancer-specific survival." (PMID 37370761, 2023). "Most of these genes were associated with cancers of metabolic systems (DUSP6, SGK1, BMP4, RASGRF1, GDF15) followed by breast cancer (CACNA2D3, ITGB7), cancers of the central nervous system (PRKCA), or leukemia (MECOM, JAK3)." (PMID 36624125, 2023).
breast cancer (continued). "With this categorization, only 25% of normal tissues were strongly positive for SGK1 compared to 50% among fibroadenoma and 53% among breast cancer tissue." (PMID 37370761, 2023). "Our study of 280 patients with well-characterized breast cancer tissue is the largest study to evaluate the expression of the SGK1 protein in breast cancer as far as we are aware." (PMID 37370761, 2023). "Here, we evaluated the level of serum/glucocorticoid-regulated kinase 1 (SGK1) and B-cell lymphoma 2 (Bcl-2) levels in the corresponding primary breast cancer tissue." (PMID 37370761, 2023). "This investigation provides crucial data regarding the expression levels of GCR, SGK1, and Bcl-2 in respective breast cancer TMAs." (PMID 37370761, 2023). "Higher cytoplasmic SGK1 staining was stronger in breast cancer tissue compared to normal tissue, especially in hormone receptor-negative cases." (PMID 37370761, 2023). "SGK1 expression in breast cancer has previously been examined in a small number of breast cancer cases." (PMID 37370761, 2023). "Here, we used the same series of breast cancer cases, from a multi-racial population with defined clinical characteristics and survival data, to measure the protein expression of SGK1 and Bcl-2." (PMID 37370761, 2023). "SGK1 was initially cloned as a gene transcriptionally stimulated by serum and glucocorticoids in rat mammary tumor cells." (PMID 35625991, 2022). "Further, consistent with our previous study, SGK1 was found to be significantly upregulated, in addition to deregulated expression of some lncRNAs, in progesterone-treated breast cancer samples." (PMID 36578092, 2022). "In particular, homologs AKT1, AKT2, ERBB2, FGFR2, and PIK3CA in CGC play important roles in breast cancer progression, mediating breast cancer risk, corresponding to the driver candidates RPS6KA1, SGK1, PTK2, IGF1R, PIK3CB, and PRKDC predicted by DriverMP." (PMID 38091511, 2022). "SGK1, a serine/threonine protein kinase, was discovered in 1993 since it was rapidly transcribed in rat breast cancer cells when stimulated by serum and/or glucocorticoids." (PMID 34898378, 2022). "The PDK1-SGK1 axis has been characterized as a drug-resistant mechanism of the PI3Kα inhibitor alpelisib in breast cancer, in which mTORC1 is activated via direct phosphorylation and inhibition of TSC2, a negative mTORC1 regulator, by SGK1." (PMID 36457711, 2022). "SGK1 has been shown to induce resistance to chemo‐ and radiotherapy in many human cancers, whereas an SGK1 inhibitor significantly increased the apoptosis of colon cancer and breast cancer cells following radiotherapy." (PMID 35106936, 2022). "SGK1 has been shown to mediate cell survival and drug resistance to platinoid and taxane compounds in breast cancer patients." (PMID 34249670, 2021). "Both mRNA and protein levels of SGK1 were upregulated in mouse and human breast cancer cell lines treated with Dex." (PMID 34272474, 2021). "The family of serine-threonine kinase consists of three members, with SGK-1 initially identified via the differential screening for glucocorticoid-inducible transcripts expressed in a rat mammary tumor cell line." (PMID 35048019, 2021). "Dexamethasone-activated GR induced the transcription of Serum/Glucocorticoid Regulated Kinase 1 (SGK) in a rat mammary tumour cell line." (PMID 33418900, 2021). "Levels of SgK1 were decreased in the hypothalamus of our mouse model of breast cancer when subjected to IS." (PMID 34305544, 2021). "This mTORC1 activation in an AKT-independent manner is regulated by Serine/threonine-protein kinase 1 SGK1 in breast cancer, and by upregulation of AXL that activates mTORC1 via Protein kinase C (PKC ) in HNSCC." (PMID 33036331, 2020). "SGK1 is identified and characterized as a tumor-promoting gene, and SGK1 dysregulation has been observed in several types of malignancies, including breast cancer, gastric cancer, lung cancer, and prostate cancer." (PMID 33542904, 2020).
breast cancer (continued). "Serum and glucocorticoid-induced protein kinase 1 (SGK1) was initially cloned as an immediate early gene transcriptionally activated by serum and glucocorticoids in rat mammary tumor cells." (PMID 33542904, 2020). "Further study indicated that SGK1 was essential for osteoclastogenesis and dramatically correlated with breast cancer bone metastasis." (PMID 33542904, 2020). "In tamoxifen-resistant human breast cancer, immunohistochemical staining analysis showed an inverse correlation between SGK1 expression and the severity of tamoxifen resistance." (PMID 33542904, 2020). "Overexpression of SGK1 significantly promotes cell migration and invasion in various cancers, including breast cancer, lung cancer, colon cancer, glioma, hepatoma, OSCC, prostate cancer, and rhabdomyosarcoma." (PMID 33542904, 2020). "SGK1 confers resistance of breast cancer cells to chemotherapy, and inhibition of SGK1 sensitizes tumor cells to cytotoxic drugs or radiation." (PMID 31225494, 2018). "A significant proportion of breast cancer cells with mutations in PTEN or Class 1 PI3K are inherently resistant to inhibitors of PI3K or Akt, as they express high levels of SGK1 that can substitute for Akt." (PMID 29150437, 2018). "High pNDRG1 staining was found in TNBC (21%) and HER2-positive tumors (12%), a finding in line with the percentage of breast cancer samples expressing high levels of SGK1 in the Cancer Genome Atlas cohort." (PMID 27451907, 2016). "Serum and glucocorticoid regulated kinase 1 (SGK1) was originally isolated in a differential screen searching for glucocorticoid-inducible transcripts in Con8.hd6 rat mammary tumor cells." (PMID 27517916, 2016). "Our results also demonstrate that, in the four Akt-inhibitor-resistant breast cancer cell lines displaying elevated SGK1 evaluated (BT-549, JIMT-1, MDA-MB-436 and HCC-1937), knockdown of SGK1 markedly suppressed cell proliferation." (PMID 23581296, 2013). "We observe in several breast cancer cells displaying high Akt activity and low SGK1 (including BT-474, CAMA-1 and T47D) that NDRG1 is still phosphorylated and that NDRG1 phosphorylation is suppressed by Akt inhibitors." (PMID 23581296, 2013). "Our findings indicate that the breast cancers most likely to be sensitive to Akt inhibitors would be those displaying high Akt, low SGK1 mRNA/protein and in which phosphorylation of NDRG1 is suppressed by Akt inhibitors." (PMID 23581296, 2013). "We identified a number of Akt-inhibitor-resistant breast cancer cells that possess elevated levels of SGK1 and present evidence that SGK1 represents a major driver of proliferation in these cells." (PMID 23581296, 2013). "Sgk1 was originally identified as an immediate early gene induced in response to serum and glucocorticoid stimuli in rat mammary tumour cells." (PMID 21079778, 2010). "The serine/threonine kinase SGK1 was originally cloned from mammary tumor cells." (PMID 41326907, 2025). "Both GR and SGK1 were expressed in the same breast cancer lesions." (PMID 39246627, 2024). "SGK1 was higher and Bcl-2 was lower in breast cancer tissue compared to normal breast tissue." (PMID 37370761, 2023). "We found that Bcl-2 expression was associated with a higher overall and breast cancer-specific survival, whereas SGK1 and GCR expression did not appear to be associated with survival." (PMID 37370761, 2023). "The molecular mechanisms underlying the association between higher SGK1 expression and breast cancer tissues is not clear." (PMID 37370761, 2023). "Here, we examined SGK1 and Bcl-2 protein expression in respective breast cancer tissue microarrays." (PMID 37370761, 2023). "SGK1 expression varied between histological and molecular breast cancer subtypes." (PMID 37370761, 2023). "SGK1 dysregulated expression was observed in hypertension, cancer, autoimmunity, and neurodegenerative disorders, and it was reported to suppress apoptosis and cellular adhesiveness in breast cancer cell lines." (PMID 37370761, 2023).